IL15 (interleukin 15)
Diseases named in the same sentence as IL15 in open-access papers (continued):
Sharing a sentence is not in itself a finding about the gene and the disease.
tumor (continued). "In the immune suppressive tumor microenvironment, TGF-β1 has been found to inhibit IL-15-promoted NK cell activation via the mTOR pathway." (PMID 37539051, 2023). "IL-15 has a critical role in the function of T- and NKT-cells and ameliorates the tumor-cell killing activity of CAR-NKT cells." (PMID 37158883, 2023). "Three-dimensional tumor models consisting of 624-MEL cells were co-cultured with human peripheral blood lymphoid cells (PBLs) in presence of the cytokines IL-2, IL-7, IL-15, IL-21 and IFN-γ." (PMID 37923822, 2023). "Up to date, there have been some approaches making CAR-T cells more persistent and enhanced anti-tumor activity in mouse tumor models, like inhibiting TCR-CD3 complex, CD155, β2-microglobulin, and EZH1, or overexpressing IL-15, IL-15R, and antigen E." (PMID 37656237, 2023). "IL-15 and IL-2 can upregulate the expression of the NKG2D activating receptor on immune lymphocytes and augment NKG2D-relevant NK cells anti-tumor cytotoxicity in melanoma patients." (PMID 36936961, 2023). "Similar to tumour tissues, we focused on comparing the immune cell changes between the IR780 + 1-MT + IL-15 + L group and NIL-IM-Lip group." (PMID 37076492, 2023). "The biNV-IL-15 treatment induced much higher TNF-α and IFN-γ secretion than IL-15+biNV in 4T1 and CT26 tumor models." (PMID 37875481, 2023). "Chronic overexposure to IL-15 of NK cells in AML has been recently described: this leads to NK exhaustion and reduced anti-tumor activity and metabolic defects." (PMID 37153603, 2023). "CRS develops in patients if T cell and tumor cell interactions lead to the release of a massive number of cytokines, such as interferon-gamma (INF-γ), TNF-α, IL-6, IL-10, and IL-15." (PMID 37443804, 2023). "Ratio differences of important immune-related AS events (clualt3p199530 NRG1, clualt5p154454 SH3BP2, clualt5p114936 ACKR3, clualt5p152292 IL15, cluir97910 NFKBIB, and clualt5p204621 IKBKG) between tumor and normal tissues are presented." (PMID 37139238, 2023). "Mice were challenged bilaterally with TRAMP-C2 cells and when they developed right flank tumors of approximately 50 mm3, they were treated intratumorally only in the right flank tumor with HBSS, cyto-IL-15, ADU-S100 or combination of cyto-IL-15 and ADU-S100." (PMID 37465665, 2023). "These cells can be stimulated in an inflammatory or tumor microenvironment by antigens secreted by the tumor or pathogen, IFN-γ itself via positive feedback, or IL-12, IL-15, and IL-18 to activate IFN-γ production." (PMID 36835413, 2023). "For example, circulating NK cells co-cultured with a head and neck SCC cell line and IL-15 upregulated CD49a and CD103, indicating promotion of a tissue-residency phenotype via the tumor microenvironment." (PMID 37448786, 2023). "The accumulation of CAR-T cells in tumor tissues can be promoted by the overexpression of CCRs from T cells (e.g., CCR2b and C-C motif chemokine receptor 4) or by the overexpression of chemokines from tumor cells (e.g., RANTES and IL-15)." (PMID 36979400, 2023). "FT596 incorporates an NKG2D-2B4ζ CAR targeting CD19 that enhances anti-tumor activity against CD19-expressing B cells, an hnCD16, and a recombinant fusion of IL-15 and IL-15 receptor alpha (IL-15RF) for cytokine-autonomous persistence." (PMID 37147740, 2023). "Reduced access to the homeostatic cytokines IL-7 and IL-15, critical for memory CD8+ T cell survival and maintenance, negatively impaired anti-tumor effector CD8+ T cell responses." (PMID 37426658, 2023). "By day 20 (survival endpoint for mice with HBSS treated TRAMP-C2 tumors), ADU reduced tumor volume by 67% and combination of ADU with IL-15 by 71% compared with vehicle; both treatments increased survival to 33 and 45 days respectively." (PMID 37465665, 2023). "KD033 targets IL-15 to PD-L1 positive cells, and in the tumor-microenvironment (TME) this would include both immune and tumor cells." (PMID 36454338, 2023).
tumor (continued). "We showed that genetically delivered IL-15/IL-15Rα acts on NK cells, CD4+ and CD8+ T cells during PBL-mediated tumor cell killing." (PMID 37923822, 2023). "They further found that granzyme C-expressing ILC1s expanded in mammary tumors and can mediate anti-tumor responses, a mechanism dependent on transforming growth factor beta (TGF-β) and IL-15 signaling." (PMID 37514187, 2023). "The temperature-sensitive NIL-IM-Lip is firstly delivered to tumours, then directed to the LNs following pH-sensitive shedding of NGR motif and MMP2-responsive release of IL-15." (PMID 37076492, 2023). "The increased activation of the cGAS/STING pathway resulted in the production of IL-15, increased activation of NK and CD8+ T cells, and an increased level of tumor cell necrosis." (PMID 36059473, 2022). "ONP-302 infusion decreased tumor growth via the activation of the cGAS/STING pathway within myeloid cells, and subsequently increased NK cell activation via an IL-15-dependent mechanism." (PMID 36059473, 2022). "In vivo, the rAAV2-IL-15 microglial cells infiltrate GBM mass and increase the recruitment of IFN-γ+ NK cells in GBM-bearing mice, with effects on tumor growth, highlighting the fundamental role of IL-15 in the tumor core to boost immune reaction." (PMID 35681612, 2022). "The IL-15 armored GD2-CAR NKT cells achieved encouraging results, as the therapeutic cells exhibited enhanced proliferation and homing to tumor sites." (PMID 35806311, 2022). "Accordingly, RANTES and IL-15 increased the accumulation of CAR T-cells at tumor sites and enhanced the sensitiveness of tumor cells to the lytic effects of CAR-T cells." (PMID 36419058, 2022). "The pro-inflammatory cytokines, such as IL-12, IL-18, and IL-15, have been used to arm CAR-T cells (the fourth-generation CAR-T cells) to enhance tumor-killing capacity." (PMID 35874698, 2022). "We examined the mRNA expression of four myokine/exerkine genes, BDNF, FNDC5, IL15, and MSTN, in tumor and paraneoplastic tissues." (PMID 36733390, 2022). "The IL-15RF was constructed by combining IL-15 and IL-15 receptor α (IL-15RA), which together are shown to further improve anti-tumor potency, survival and proliferation in transduced CD8+ T cells compared to IL-15 or IL-15RA alone." (PMID 36348457, 2022). "Therapy with IL‐15 superagonist, ALT-803, has been reported to boost anti-tumor activity of NK and T cells and prolong patient survival." (PMID 36246629, 2022). "Further, we prove that similar vector designs can be applied in PAX3-FOXO1-driven ARMS, and to express immunomodulatory cytokines, such as IL-15 and XCL1, in tumor entities typically considered to be immunologically ‘cold’." (PMID 36229873, 2022). "Compared to those of tumor-bearing mice, the expression levels of stimulatory molecules, including CXCL10, IL-12, and IL-15, were significantly upregulated, while the expression level of IL-7 was downregulated." (PMID 36389684, 2022). "For example, IL-15 incorporated into the CAR construct enhanced NK cell cytotoxicity and eliminated tumor cells." (PMID 36246629, 2022). "Superior tumor control and improved survival were evident in mice treated with OMCPmutIL-2–expanded CD8+ T cells compared with those expanded by either IL-2 or IL-15." (PMID 35603788, 2022). "Pre-clinical studies support the benefit of transgenic cytokines like IL15 and IL7 in augmenting the CAR T cell anti-tumor response; first clinical trials are evaluating safety and efficacy of the approach." (PMID 36700225, 2022). "NKTR-255, a recombinant human IL-15 (rhIL-15) receptor agonist, can activate the IL-15 pathway and promote the proliferation of memory CD8+ T cells and Tscm subsets in tumor-specific T-cell colonies." (PMID 35320942, 2022). "As IL-15 has been shown to strengthen the anti-tumor response, we have modified CD4 CAR to secrete an IL-15/IL-15sushi complex." (PMID 36172388, 2022). "Furthermore, IL-21 might yield a superior anti-tumor activity as compared to IL-15." (PMID 36358860, 2022).
tumor (continued). "Mice that received IL-15 after priming of NK cells with CHIR99021, displayed better tumor control demonstrating that inhibition of GSK3 promotes NK cell antitumor activity after adoptive transfer." (PMID 36569860, 2022). "Accordingly, hyperacetylation/upregulation of oncogenes related with angiogenesis and vascular invasion (COL24A1, NDP and HOXA13) and hypoacetylation/downregulation of angiogenesis-tumor suppressor genes (CD40 and IL15) was identified in this study." (PMID 35740301, 2022). "Among which, the expressions of anti-tumor cytokines including IL-2, IL-15 IL-17A, IFN-γ and TNF-α were up-regulated, while tumor-promoting cytokines including IL-4 and IL-10 were down-regulated in HER2.28ζ/PD-L1.BB CAR-T cells." (PMID 36402752, 2022). "Oncolytic viruses increase the infiltration and efficacy of CAR-T cells in tumor sites through the production of RANTES, CXCL11, and IL-15." (PMID 36419058, 2022). "Then, we examined the mRNA expression levels of BDNF, FNDC5, IL15, and MSTN, in tumor tissues and paracancerous tissues." (PMID 36733390, 2022). "CISH−/− iNK cells expand and display in vitro short-term and long-term cytotoxicity, IFN-γ production and degranulation capacity against multiple tumor targets (K562, MOLM and SKOV3 cells) at IL-15- or IL-2-limiting conditions." (PMID 36445164, 2022). "The kinetics of the apoptotic signal varied for the different tumor spheroids, and for OVCAR-3 the apoptotic signal induced by IL12/15/18- generated EV was higher at day 2 compared to IL-15-generated EVs (p = 0.02 and p = 0.003, respectively)." (PMID 35119498, 2022). "The mRNA expression of BDNF, IL15, and MSTN were significantly higher in tumor tissues than in paraneoplastic tissues, while the expression of FNDC5 was significantly reduced in tumor tissues." (PMID 36733390, 2022). "In order to concentrate IL-15 efficacy within the TME and likely improve its efficacy, intratumoral delivery of plasmid IL-15 DNA has been evaluated in experimental tumor models." (PMID 36231109, 2022). "Within the tumor microenvironment, HSC‐engrafted NSG‐Tg(Hu‐IL15) mice maintained higher CD56dim/CD16+ NK cell percentages and numbers as compared to tumors from HSC‐engrafted NSG mice after CD8+ T‐cell depletion." (PMID 35959876, 2022). "In this study, we compared the tumor-targeting potential of EVs derived from either primary NK cells or the NK cell lines NK-92 and KHYG-1 cultured in IL-15 alone or in combination with IL-12 and IL-18." (PMID 35119498, 2022). "A promising approach is the deletion of the CISH gene, coding for the negative regulator of IL-15 signaling CIS, which leads to improved NK cell metabolic profile, increased in vivo persistence and anti-tumor function of NK cells." (PMID 36348457, 2022). "Then, we evaluated the efficacy of HSV-2 vectors expressing IL-12, IL-15, PD-1v, GM-CSF, and IL7 × CCL19 using syngeneic CT26 tumor-bearing model." (PMID 35459242, 2022). "This novel CD4-IL15/IL15sushi CAR then demonstrated potent in vitro and in vivo anti-tumor efficacy in multiple CD4+ cell lines, confirming that the addition of the IL15/IL15sushi complex enhanced anti-tumor targeting and killing." (PMID 36172388, 2022). "IL-4, IL-6 and IL-10 are abundantly expressed in TME and play more pro-tumor role, while IL-2, IL-12, IL-15 and IL-18, which are immunomodulatory or pro-inflammatory factors, are restricted in the TME and play more anti-tumor role." (PMID 36698392, 2022). "Oncolytic viruses have also been modified to encode IL-12, alone or along with other molecules (GM-CSF or IL-15), in order to promote and enhance both CD8 T and NK cell-mediated anti-tumor responses." (PMID 36231109, 2022).
tumor (continued). "To further stress the in vitro system, we set up a second tumor re-challenge assay in which CAR T cells were expanded for 10 days in the presence of IL-7 and IL15, co-cultured with Namalwa cells at E:T ratio of 1:1 and challenged every day." (PMID 36275777, 2022). "Cytokine signalization components have been modified to boost CAR-NK activity by incorporating the inducible MyD88/CD40 (iMC) system as an independent co-stimulator of an IL-15 secreting CAR-NK to enhance cell persistence and tumor control." (PMID 35990652, 2022). "The combination therapy of oHSV2-IL12, -IL15, GM-CSF, -PD1v, and IL7 × CCL19 exhibited the highest tumor inhibition efficacy compared with the treatment of single OV or two OVs combination." (PMID 35459242, 2022). "When the tumor became palpable, CD8+ T cells were depleted from half of the NSG‐Tg(Hu‐IL15) mice using OKT‐8 depleting antibody as described in the Materials and Method." (PMID 35959876, 2022). "Whereas after tumor cell invasion, osteoclastogenesis is promoted by the release of osteoprotegerin (OPG) and cytokines (IL6, IL15 etc.), leading to bone destruction." (PMID 35388653, 2022). "We found that four muscle failure-related genes (BDNF, FNDC5, IL15, MSTN) were significantly increased in tumor cells." (PMID 36733390, 2022). "In the current study, IL-15 was introduced to NKG2D CAR T cells, and the resulting 15×19 CAR T cells secreted high levels of IL-15 and massively expanded upon stimulation by tumor antigens." (PMID 36618357, 2022). "ALT-803 enhances the tumor killing activity of NK and CD8+ T cells and has a longer half-life than recombinant IL-15, leading to a potent antitumor effect." (PMID 36439125, 2022). "The pro-inflammatory cytokines and other soluble factors present in TME such as, IL-15, IL-2, IL-21, IFN-α, and GM-CSF further enhance the anti-tumor characteristic of DC." (PMID 36253762, 2022). "However, type I IFNs, IL-12, IL-15 and IL-18 are produced by activated antigen presenting cells and other cell types that are often present in the tumor microenvironment, thus suggesting that an innate immune response may be important in the host anti-tumor response." (PMID 36330506, 2022). "In this manuscript, we reported that a newly developed recombinant human IL15 fused with albumin binding domain (hIL15-ABD) showed superior biological half-life, pharmacokinetic and anti-tumor immunity than wild-type (WT) hIL15." (PMID 33918641, 2021). "The CAR enhances anti-tumour activity against CD19 expressing B-cells, while the CD16 receptor increases ADCC, and the IL-15/IL-15r fusion receptor promotes in vivo persistence and expansion of the engineered iPSC-NK cells." (PMID 34897554, 2021). "Additionally, as IL-15 is a potent stimulator of T cells and NK cells, the presence of a secreted IL15/IL15sushi complex might stimulate the normal host response against the tumor, preventing residual disease or relapse with antigen-negative cells, but this idea requires more testing as well." (PMID 33410096, 2021). "Transgenic IL-15 expressing IL13Rα2-CAR T cells had greater expansion and enhanced anti-tumor effector function as measured by cytokine production." (PMID 34421912, 2021). "In contrast, patients with a Grade 3 tumor with a favourable OS and DFS demonstrated significantly decreased IL-15 values." (PMID 32929618, 2021). "While long-term T cell culture in IL-2 drives terminal differentiation, the common γ-chain cytokines IL-7 and IL-15 have been reported to promote a central memory T cell (TCM cell) phenotype enabling superior persistence and in vivo tumor control upon ACT." (PMID 33156338, 2021). "We show proof of this principle here, whereby IL-15 stimulation significantly augmented ICI, as demonstrated by enhanced tumor regression." (PMID 34081628, 2021).
tumor (continued). "Therefore, similarly to IL-15, an altered SMAD-3 activity associated with specific genetic variants could modify the TGF-β-related transcriptional response impacting on both the tumor development and the antitumor FOLFIRI efficacy, finally affecting the patients’ prognosis." (PMID 33916844, 2021). "Post-conditioning increases in IL-15 plasma concentration have been identified as an important factor affecting CAR-T cell expansion, anti-tumor activity and toxicities including ICANS and CRS." (PMID 34712233, 2021). "IL-15 primarily stimulates proliferation and cytotoxic functions of NK and CD8 T cells leading to enhanced anti-tumour responses." (PMID 33446741, 2021). "Constitutive expression of IL-15 by first generation CD19-CAR T cells improved their in vivo antitumor activity and allowed cells to persist in mice for up to 110 days after tumor challenge." (PMID 34177932, 2021). "On days 4 and 7 after tumor implantation, the mice were treated with MMC-inactivated IL-15:IL-15Rα-B16F10-OVA by s.c. injection at nearby sites." (PMID 34439192, 2021). "Functionally, tumor-induced immature NK cells had decreased ability to control tumor growth in vivo and exhibited decreased IFN-γ production in response to in vitro stimulation with IL-15." (PMID 35082797, 2021). "generated a B7-H3/IL-15 TriKE that used the scFv of the B7-H3-specific mAb 376.96; when deployed against PDAC, this TriKE resulted in a significant reduction in tumor load in vitro and in murine models." (PMID 34349762, 2021). "Therefore, linking IL-15 treatment to a tumor-targeting agent could reduce off-target toxicity." (PMID 34681717, 2021). "The IL-15 supplementation to NK cells using this molecule, ALT-803, demonstrated improved anti-tumor outcomes in preclinical models and phase I clinical trials." (PMID 34445750, 2021). "Immunization with this IL-15:IL-15Rα cancer vaccine delayed tumor growth in mice by inducing effector memory CD4+ and CD8+ cells and effector NK cells which are tumor-infiltrating." (PMID 34439192, 2021). "BiKEs induce NK cell killing by binding to CD16 on the surface of NK cells and a tumor antigen simultaneously, while TriKEs target CD16, a tumor antigen, and an IL-15 molecule to activate the NK cells." (PMID 33968039, 2021). "CISH−/− NK cells are hypersensitive to IL-15 and, as a result, CISH−/− mice are resistant to experimental tumor metastasis." (PMID 33946954, 2021). "Bortezomib was shown to increase miR-29b expression and block the IL-15/miR-29b/BDR4 loop in vitro and prevent tumor progression in murine models of CTCL15." (PMID 33628583, 2021). "Infiltration of the infused immune cells into the tumor microenvironment is critical for successful immunotherapy, and CIML NK cells exhibited strikingly higher numbers in the tumors compared with IL-15-pretreated NK cells." (PMID 34863287, 2021). "As IL-15 strengthens the anti-tumor response, we have modified CD5 CAR to secrete an IL-15/IL-15sushi complex." (PMID 33410096, 2021). "IL-15-expanded CAR T cells also exhibit an enhanced proliferative capacity and anti-tumor function in vivo in part through reduced mammalian target of rapamycin complex 1 (mTORC1) signaling, which enforces a Tscm phenotype." (PMID 34899716, 2021). "After stimulation, the percentage of C02-Activated-IFNG and C06-Activated-IL2RA of TCR-TMART-1 was downregulated, while the fragment of C01-Activated-CD69, C11-Activated-IL15, and C12-Cytotoxic-GNLY was upregulated with increased tumor PD-L1 levels." (PMID 33754038, 2021). "This further suggests IL-15 is a potent inducer of NK cell chemotaxis and can overcome fractalkine-mediated decreases in NK cell migration towards OAC tumours." (PMID 35008227, 2021). "This work presents robust tools for the transduction and expansion of murine CAR-T cells and demonstrates the impact of murine IL-15 co-expression on CAR-T cell expansion, phenotype, function, and tumor microenvironment reprogramming in immunocompetent mice." (PMID 33156338, 2021).